VANGL1 (VANGL planar cell polarity protein 1)
Synonyms: LPP2; STB2; KITENIN; STBM2
Tractability: Small molecule: a structure with a bound ligand is known. Antibody: UniProt places it where antibodies can reach, with medium confidence; UniProt predicts a signal peptide or a membrane-spanning region; its Gene Ontology location is reachable by antibodies, with medium confidence; the Human Protein Atlas places it where antibodies can reach. PROTAC: ubiquitination databases record sites on it.
Gene: Protein-coding gene on chromosome 1 (115,641,854 to 115,698,224, forward strand). Ensembl gene ENSG00000173218.
Subcellular location: Cell membrane
Subcellular location (Human Protein Atlas): Plasma membrane
Pathways (Reactome):
Signal Transduction: CDC42 GTPase cycle; RAC1 GTPase cycle; RAC2 GTPase cycle; RAC3 GTPase cycle; RHOA GTPase cycle; RHOB GTPase cycle; RHOC GTPase cycle; RHOD GTPase cycle; RHOF GTPase cycle; RHOG GTPase cycle; RHOH GTPase cycle; RHOJ GTPase cycle; RHOQ GTPase cycle; RHOU GTPase cycle; RHOV GTPase cycle; RND1 GTPase cycle; RND2 GTPase cycle; RND3 GTPase cycle
Gene Ontology:
Molecular function: protein binding
Biological process: Wnt signaling pathway, planar cell polarity pathway
Cellular component: plasma membrane; lateral plasma membrane; membrane
Genetic constraint (gnomAD): Loss-of-function variants: 18 observed, 50.24 expected, observed/expected ratio (o/e) 0.36, 90% interval 0.25 to 0.53. The upper end of that interval is the gene's LOEUF score, 0.53, which puts it in group 2 of 6, group 1 being the genes least tolerant of losing a copy. Missense variants: 667 observed, 710.8 expected, observed/expected ratio (o/e) 0.94, 90% interval 0.88 to 1. Synonymous variants: 257 observed, 277.13 expected, observed/expected ratio (o/e) 0.93, 90% interval 0.84 to 1.03.
Homologues: Orthologues: chimpanzee VANGL1 (99% identical), dog VANGL1 (97% identical), rabbit VANGL1 (97% identical), pig VANGL1 (96% identical), mouse Vangl1 (95% identical), rat Vangl1 (95% identical), macaque VANGL1 (95% identical), guinea pig VANGL1 (92% identical), zebrafish vangl1 (66% identical), tropical clawed frog VANGL1 (50% identical), Drosophila melanogaster Vang (49% identical), Caenorhabditis elegans vang-1 (34% identical). Paralogues in human: VANGL2 (73% identical).
Diseases named in the same sentence as VANGL1 in open-access papers:
VANGL1 is named in the same sentence as 45 diseases in open-access papers, as found by Europe PMC text mining. Sharing a sentence is not in itself a finding about the gene and the disease. The quoted sentences say what the papers report.
breast cancer (12 papers, 2012 to 2026). A primary or metastatic malignant neoplasm involving the breast. "Both Vangl1 and Vangl2 are found to be overexpressed in breast cancers and are associated with poor prognosis and have been implicated in tumor growth or cancer cell migration." (PMID 33990333, 2021). "A high level of VANGL1 expression is associated with poor prognosis and relapse in breast cancer patients." (PMID 31068622, 2019). "This could be relevant as linkage of scoliosis to e.g. VANGL1, which is also linked to breast cancer is discussed." (PMID 40940639, 2026). "Breast cancer cells overexpressing Vangl1 or Vangl2 exhibit increased motility and Dvl2 phosphorylation compared to cells transduced with control lentivirus and display a distinctive hyper-protrusive leading-edge morphology." (PMID 37147680, 2023). "We observed that Vangls localize to the leading edge of singly and collectively migrating breast cancer cells and that high expression of Vangl1 or Vangl2 in leader cells results in a hyper-protrusive leading edge." (PMID 37147680, 2023). "In breast cancer, VANGL1 co-localizes with SCRIBBLE and NOS1AP (Nitric Oxide Synthase 1 Adaptor Protein) in cellular protrusions and regulates the migration of cells." (PMID 36675340, 2023). "It should also be noted that analyses of other series have disclosed worse survival outcomes in breast cancers over-expressing SCRIBBLE or VANGL1 mRNA." (PMID 36675340, 2023). "We employed immunofluorescence microscopy to assess the localization of endogenous and ectopically expressed Wnt/PCP components Vangl1 and Vangl2 in singly and collectively migrating breast cancer cells." (PMID 37147680, 2023). "Here, Fzd6 and Dvl1 localized to the protrusive fronts of migratory breast cancer cells while Vangl1 was observed to localize to the base of migratory protrusions with Pk1." (PMID 35646914, 2022). "In human breast cancer cells, prior studies have shown that Vangl1 and Vangl2 promote cancer cell proliferation or migration." (PMID 33990333, 2021). "Protein extracts of breast cancer cell lines either expressing only Vangl1 (T47D, MDA-MB-231) or expressing concomitantly Vangl1 and Vangl2 (SKBR7, SUM149), were evaluated for Vangl2 expression by western blots probed with 2G4 mAb." (PMID 23029439, 2012). "Vangl1 mRNA has a broad expression in all tested breast cancer cell lines whereas Vangl2 mRNA is more selectively expressed and only detectable in a limited number of cell lines." (PMID 23029439, 2012). "Our findings that high expression of Vangl1 or Vangl2 results in a hyper-protrusive leading edge suggest that Vangl localizes to the protrusive leading-edge membrane of leader cells in migrating breast cancer cell cohorts to regulate the cytoskeleton." (PMID 37147680, 2023). "Here, we examine the contribution of Wnt/planar cell polarity (Wnt/PCP), one of the non-canonical Wnt signaling pathways and defined by the involvement of the tetraspanin-like proteins Vangl1 and Vangl2, to breast tumor cell motility, collective cell invasiveness and mammary tumor metastasis." (PMID 37147680, 2023). "Indeed, elevated Vangl1 expression significantly increases both the number of Vangl1-rich protrusions in leader cells and the percentage of leader cells with Vangl1-rich protrusions in a collectively migrating sheet of MCF7 breast cancer cells." (PMID 37147680, 2023). "Although Vangl1 may compensate for loss of Vangl2 in some contexts, Vangl1 transcript is not significantly altered in Vangl2fl/fl/NDL mammary tumors relative to Vangl2+/+/NDL tumors." (PMID 37147680, 2023). "When the miR-101-5p-associated pathways in breast cancer were assessed using RNA-seq, a particular group of genes, HMGB3, ESRP1, GINS1, TPD52, SRPK1, VANGL1, and MAGOHB, were suggested to be associated with a poor prognosis of BC." (PMID 38132441, 2023). "We observe Vangl1 and Vangl2 localization to the leading edge of migrating MDA-MB-231 breast cancer cells within actin-rich migratory protrusions." (PMID 37147680, 2023).
breast cancer (continued). "Vangl1 and Vangl2 knockdown and overexpression and Wnt5a stimulation were employed to manipulate Wnt/PCP signaling in a battery of breast cancer cell lines representing all breast cancer subtypes, and in tumor organoids from MMTV-PyMT mice." (PMID 37147680, 2023). "While alterations of VANGL1 and VANGL2 in breast cancer have been investigated, their function in normal breast development is still unknown." (PMID 31068622, 2019). "In metastatic breast cancer cells induced by stromal Wnt11-containing exosomes, Fzd6 and Vangl1 exhibit mutually exclusive localizations, with Fzd6 on the leading edge of cell protrusions and Vangl1 on non-protrusive cell surfaces, and knock-down of either protein decreases cell motility." (PMID 26990447, 2016). "Vangl1 and Vangl2 fused to an N-terminal GFP tag were expressed in T47D cells, a breast cancer cell line that does not express endogenous Vangl2 at the mRNA level." (PMID 23029439, 2012).
bladder cancer (9 papers, 2018 to 2025). "circRNA VANGL1 (circVANGL1), derived from two exons of the Van Gogh-like 1 (VANGL1) gene, was previously identified as an oncogene in human bladder cancer." (PMID 35300347, 2022). "Circ-VANGL1 overexpression in bladder cancer can also drive oncogenesis via the miR-605-3p-VANGL1 axis." (PMID 35974419, 2022). "High-throughput microarray analysis and previous evidence suggested that circRNA VANGL1 (circ_VANGL1) (circBase ID: hsa_circ_0002623) was aberrantly expressed in bladder cancer." (PMID 34258391, 2021). "circRNA VANGL1 (circVANGL1) is generated from two exons of the Van Gogh‐like 1 (VANGL1) gene and serves as a tumour promoter in bladder cancer." (PMID 34750955, 2021). "In bladder cancer, overexpression of circ‐VANGL1 promotes cancer development by regulating the miR‐605‐3p‐VANGL1 pathway." (PMID 32378344, 2020). "For example, inhibition of circRNA VANGL1 can inhibit bladder cancer progression." (PMID 36092922, 2022). "In the present study, we observed that miR-145-5p inhibitor could partially reverse the effects of circ_VANGL1 deletion on cell viability, apoptosis, and the resistance to doxorubicin, suggesting a regulatory network of circ_VANGL1/miR-145-5p in bladder cancer progression." (PMID 34258391, 2021).
colorectal cancer (9 papers, 2016 to 2025). A primary or metastatic malignant neoplasm that affects the colon or rectum. "For instance, Vangl1 has been shown to both inhibit colorectal carcinoma metastasis in mice but also to promote and induce colorectal cancer metastasis in the same mouse model." (PMID 27036398, 2016).
colon carcinoma (8 papers, 2009 to 2024). "VANGL1 (also known as KITENIN or STB2) acts as an executor in colon cancer cells with regard to cell motility and thereby controls cell invasion, which may contribute to promoting metastasis." (PMID 20015385, 2009).
glioblastoma (5 papers, 2017 to 2026). The most malignant astrocytic tumor (WHO grade IV). "It was observed that VANGL1 and VANGL2 are highly up-regulated in glioblastoma (GBM) progression and promote cell invasion and migration." (PMID 41385185, 2025). "In our co-immunoprecipitation and mass spectrometry analysis for SFRP2-interactors we instead detected other non-canonical WNT-signaling components including VANGL1, a transmembrane protein associated with non-canonical WNT-signaling recently reported to alter cell motility in glioblastoma." (PMID 34021259, 2021).
spina bifida (5 papers, 2013 to 2025). A congenital neural tube defect in which vertebrae are not fully formed. "As in the exome dataset of proband SB1A with the EFNB1 variant (rs772228172), four variants were annotated as homozygous (CUBN, COMT, PTCH1 and TRDMT1) and eight variants as heterozygous (CUBN,MTRR, and VANGL1) in the reported spina bifida-related genes." (PMID 35741713, 2022). "Genetic factors including variations in some specific genes such as MTHFR, MTHFD1, MTRR, VANGL1, VANGL2, CELSR1, and FUZ, as well as variants in the T-locus on chromosome 6q have also been studied in the development of spina bifida and other spinal dysmorphisms." (PMID 39835283, 2025). "Alternatively, as almost all of these variants were identified in heterozygous patients, dimerization with wild type VANGL2 or VANGL1 may impair normal pathway activity with variable penetrance; a notion supported by the low incidence of spina bifida in heterozygous Vangl2 mutant mice." (PMID 37815931, 2024). "Methylation of VANGL1 was 0.17% (P-value = 0.063) higher and of LEKR/CCNL 1.36% higher (P-value = 0.048) in spina bifida cases as compared to controls." (PMID 24223810, 2013).
hepatocellular carcinoma (4 papers, 2013 to 2026). A malignant tumor that arises from hepatocytes. "Indeed, the suppression of VANGL1 expression has been associated in vitro to the inhibition of the hepatocellular carcinoma growth." (PMID 23638078, 2013). "Expression of the PCP core protein Prickle1 is downregulated in hepatocellular carcinoma whereas both Prickle1 and Vangl1 expression inhibit hepatocellular carcinoma growth in vitro." (PMID 27036398, 2016).
lung carcinoma (4 papers, 2015 to 2022). "In lung cancer, IGF2BPs, in particular, the IGF2BP2/3 increase the mRNA stability of VANGL1, and VANGL1 is associated with radio-resistance." (PMID 35541906, 2022).
melanoma (4 papers, 2021 to 2022). A malignant, usually aggressive tumor composed of atypical, neoplastic melanocytes. "Interestingly, the expression of two genes encoding direct targets ubiquitinated by RNF43, namely, DVL3 and VANGL1, increased during melanoma progression and high expression in both cases correlates with bad prognosis and shorter overall survival." (PMID 34702444, 2021). "In melanoma cells, miR-150-5p sponged circular RNA VANGL1, which might promote the proliferation, migration and invasion of melanoma cells." (PMID 34944871, 2021).
osteoporosis (3 papers, 2022 to 2024). A condition of reduced bone mass, with decreased cortical thickness and a decrease in the number and size of the trabeculae of cancellous bone (but normal chemical composition), resulting in increased fracture incidence. "As miR-217 has been shown to sponge different circRNAs, such as circ-VANGL1 and promote osteoporosis development by downregulating RUNX2 expression, or circRNA_100367 it would be interesting that future studies explore circRNAs/miR-217 interactions and SIRT1 regulation in OA chondrocytes." (PMID 38136977, 2023). "A similar effect has been reported for circ-VANGL1, whose decreased expression in BMSCs isolated from osteoporosis patients was related to the negative modulation of RUNX2 and osteoporosis promotion." (PMID 38164139, 2024). "Circ_VANGL1 also regulates the progression of non-tumor diseases, and its expression is downregulated in osteoporosis, when compared with non-osteoporosis patients." (PMID 35205613, 2022).
lung adenocarcinoma (2 papers, 2020 to 2022). A carcinoma that arises from the lung and is characterized by the presence of malignant glandular epithelial cells. "In lung adenocarcinoma, radiation causes the reduction expression of miR-29b-3p, which targets VANGL1, thus increasing the expression of VANGL1 in cancer." (PMID 35022030, 2022). "Knockout VANGL1 can harm DNA from damage by activating BRAF-TP53BP1-Rad51 cascade, enhances the harmful effects of radiation on lung adenocarcinoma." (PMID 35022030, 2022).
breast tumor (1 paper, 2023). "To investigate this possibility, we stably overexpressed Vangl1 or Vangl2 via lentiviral infection in human and mouse breast tumor cell lines." (PMID 37147680, 2023).
caudal regression syndrome (1 paper, 2020). "Mutations in VANGL1 have previously been associated only with caudal regression syndrome, a rare neural tube defect disease with an abnormal development of the vertebral column and spinal cord." (PMID 32278351, 2020).
chronic rhinosinusitis (1 paper, 2018). Chronic form of sinusitis. "Although there are no reports showing that external fluid flow controls the direction of ciliary movement in airway epithelium, asymmetric Vangl1 crescents are known to disappear at the area without ciliated cells in the sinonasal epithelia of humans with cystic fibrosis or chronic rhinosinusitis." (PMID 29394896, 2018).
colon adenocarcinoma (1 paper, 2021). "Results showed that VANGL1 and EGFR proteins were overexpressed (more than 50% of the stained cells in colon adenocarcinoma tissues compared with the normal tissues)." (PMID 33672900, 2021).
gastric tumors (1 paper, 2011). "Furthermore, inhibition of VANGL1, an essential component of Wnt/PCP pathway that is overexpressed in SCC, was found to inhibit the size and metastatic potential of gastric tumors in mice." (PMID 22016777, 2011).
nasal polyp (1 paper, 2023). "No immunoreactivity was observed in either the turbinate mucosa or nasal polyp for Prickle1 or Vangl1." (PMID 38232516, 2023). "The expression levels of DVL1, DVL3 and FZD3 mRNAs were significantly lower in the nasal polyps than in the turbinates, while those of FZD6, PRICKLE1, PRICKLE2, VANGL1 and VANGL2 mRNAs were not statistically different between the two tissues." (PMID 38232516, 2023).
neuroblastoma (1 paper, 2018). Neuroblastoma (NB) is the most common solid, extracranial childhood tumor. "The inference from our work that Wnt signalling may have a pro-differentiation and tumour suppressive influence is supported by the recent identification of Wnt pathway mutations in neuroblastoma, which include probable loss of function mutations of LEF1 and VANGL1." (PMID 29505958, 2018).
polycystic kidney disease (1 paper, 2023). A usually autosomal dominant and less frequently autosomal recessive genetic disorder characterized by the presence of numerous cysts in the kidneys leading to end-stage renal failure. "Additionally, Wnt/PCP is considered a factor involved in polycystic kidney disease development through gene mutations such as CELSR1, CELSR2, CELSR3 (representing cadherin EGF LAG seven-pass G-type receptor 1/2/3), VANGL1 and VANGL2 (representing Vang-like protein 1/2)." (PMID 37762322, 2023).
prostate carcinoma (1 paper, 2018). A carcinoma that arises from epithelial cells of the prostate gland. "Genes encoding FZD2-5, FZD8, VANGL1, ROR1, RYK, LGR4, LRP5 and 6, and GPC4 were highly expressed in at least three prostate cancer cell lines." (PMID 29717114, 2018).
rapidly progressive glomerulonephritis (1 paper, 2021). Inflammation of the glomeruli that is characterized by a rapid loss in renal function with glomerular crescent formation observed on biopsy; it is often seen in patients with concomitant autoimmune disease, like Goodpasture's syndrome or systemic lupus erythematosus. "The NTN model mirrors human rapidly progressive glomerulonephritis (RPGN), and recently, transcripts for VANGL1, VANGL2, CELSR2, DVL2, DVL3, PK1, and PK2 were found to be significantly upregulated in two independents cohorts of RPGN biopsies compared to living kidney donor controls." (PMID 33716764, 2021).
Spinal dysraphism (1 paper, 2011). A heterogeneous group of congenital spinal anomalies that result from defective closure of the neural tube early in fetal life. "Later, mutations in Vangl1 were detected in spinal dysraphisms, providing further evidences to support the role of Vangl1 as a risk factor in the development of spinal NTDs." (PMID 21864354, 2011).
Strabismus (1 paper, 2015). A misalignment of the eyes so that the visual axes deviate from bifoveal fixation. "Vangl1 is a highly conserved, structurally similar paralogue of Vangl2, and is the only other known mammalian orthologue of Drosophila strabismus/Van Gogh." (PMID 25264362, 2015).